INS (insulin)
Diseases named in the same sentence as INS in open-access papers (continued):
Sharing a sentence is not in itself a finding about the gene and the disease.
cognitive decline (continued). "A large number of studies in the last two decades suggest that central insulin resistance and cognitive decline in AD are associated with changes in the neuronal insulin/IR signal transduction cascade, insulin grow factor 1 (IGF-1) resistance and insulin receptor substrate 1 (IRS-1) dysregulation." (PMID 37445790, 2023). "In the HC pattern, a high intake of refined grains may stimulate insulin secretion and associated cognitive decline." (PMID 36771475, 2023). "Impaired insulin signaling is responsible for the neuronal loss and cognitive decline in AD." (PMID 33584324, 2020). "An ongoing Phase II/III clinical trial in amnestic MCI and mild AD subjects (SNIFF: Study of Nasal Insulin to Fight Forgetfulness) will determine the effects of intranasal insulin on cognitive decline, brain volume loss, and changes in CSF biomarkers (NCT01767909)." (PMID 30541602, 2018). "First, reductions in adiposity and increases in muscle mass, which are targeted by PRT, have been specifically associated with improved insulin sensitivity, glucose control, and inflammation, which are in turn associated with a decreased risk of cognitive decline." (PMID 29387262, 2018). "Appropriate neuronal insulin sensitivity and signaling are vital for the maintenance and formation of new synapses, and the loss of neuronal IR is thought to significantly contribute to Aβ-induced cognitive decline." (PMID 29973867, 2018). "Therefore, we aim to assess the association between changes in plasma levels of IGF-1 and insulin and the cognitive decline in HD patients over time, in a prospective multicentric cohort study." (PMID 27627435, 2016). "In summary, the current study demonstrated that chronic APN deficiency might lead to cognitive decline and AD-like pathologies through insulin desensitization." (PMID 27884163, 2016). "Also in the absence of T2D, impaired glucose regulation and higher serum insulin concentrations were found to increase the risk of cognitive decline." (PMID 26074813, 2015). "Moreover, ASK1 is associated with insulin signal transduction, an important signaling component in cognitive decline." (PMID 24481061, 2014). "Furthermore, higher levels of fasting insulin were associated with faster rates of cognitive decline." (PMID 22654904, 2012). "Taken together, insulin in the short run might improve cognition, but chronically elevated insulin levels are associated with faster cognitive decline during aging." (PMID 22654904, 2012). "Taken together, these findings suggest that brain insulin signaling is associated with late-life cognitive decline and that AKT1 phosphorylation may be preferentially associated with a decline in memory, whereas IRS1 phosphorylation may be preferentially associated with perceptual speed." (PMID 38029396, 2024). "Thus, changes in insulin levels and/or signaling in the brain could lead to neuronal loss and synaptic dysfunction associated with cognitive decline and the disruption of peripheral metabolism." (PMID 36499613, 2022). "In conclusion, drawing the molecular signature underlying alterations of insulin signaling in DS is a key challenge to identifying novel drug targets and set-up new prevention strategies aimed to reduce metabolic disorders as well as their impact on cognitive decline in DS." (PMID 32733190, 2020). "CDCA is thought to improve AD neurotoxicity and cognitive decline by enhancing insulin signaling,which shows that CDCA exerts beneficial effects on the brain." (PMID 40076732, 2025). "Impaired insulin signaling disrupts these processes, contributing to cognitive decline and neurodegeneration." (PMID 40724831, 2025). "Chronic overnutrition and neuroinflammation exacerbate these impairments, promoting hypothalamic leptin and insulin resistance, hallmarks of metabolic disease and contributors to cognitive decline." (PMID 41409607, 2025).
cognitive decline (continued). ": These drugs improve the insulin sensitivity and lower oxidative stress, but the long-term effects of these drugs on cognitive decline are still being studied." (PMID 41003796, 2025). "ApoE4 exacerbates Alzheimer's‐like pathologies in T2DM by activating GSK‐3β and disrupting insulin signaling, leading to tau hyperphosphorylation, neuroinflammation, and cognitive decline." (PMID 40905109, 2025). "The comparable performance of these two insulin sensitivity markers emphasizes the fundamental role of insulin resistance in cognitive decline, consistent with their common physiological basis in glucose metabolism regulation." (PMID 40538401, 2025). "In contrast, Western-style diets high in refined sugars, saturated fats, and processed foods tend to promote oxidative stress, insulin resistance, and low-grade inflammation, thereby exacerbating cognitive decline over time." (PMID 40001727, 2025). "Cognitive decline and low HL levels hinder insulin dosing accuracy, glycemic trend interpretation, and the effective use of digital self-management tools." (PMID 40566297, 2025). "This signifies that memory function serves both as an early indicator of cognitive decline and as a sensitive marker of metabolic abnormalities—such as insulin resistance—within the cognitive domain." (PMID 41488045, 2025). "Impaired insulin signaling is believed to exacerbate these processes, thus emphasizing the connection between insulin resistance and cognitive decline." (PMID 41294899, 2025). "In both disorders, constant inflammation induces insulin resistance, what next exacerbates neurodegeneration and cognitive decline." (PMID 40818936, 2025). "Concomitant deficits in GLUT3/GLUT4 trafficking and IDE competition with circulating insulin can aggravate Aβ accumulation, synaptic failure, and cognitive decline." (PMID 41155642, 2025). "In older adults with T1DM, even modest cognitive decline can have disproportionately serious consequences given the complexity of insulin dosing and device management." (PMID 41179041, 2025). "Eating behavior and appetite changes should be explored further as possible side effects of intranasal insulin treatment for cognitive decline in diverse populations." (PMID 40980544, 2025). "Adiponectin/resistin ratios correlate with insulin sensitivity, systemic inflammation, and cognitive decline." (PMID 41155642, 2025). "T2DM shares several pathophysiological features with AD, including impaired glucose metabolism, insulin resistance, inflammation, amyloid protein accumulation, and cognitive decline." (PMID 40905109, 2025). "Fecal microbiota transplantation has demonstrated potential in alleviating diabetes-related cognitive decline by altering gut microbiota composition and enhancing brain insulin signaling pathways." (PMID 40831951, 2025). "This neuro-metabolic crosstalk forms a feedback loop in which central insulin resistance disrupts neurotransmitter signaling, exacerbating glycemic imbalance, appetite dyscontrol, and cognitive decline." (PMID 40869170, 2025). "Neuroinflammation is another significant factor that contributes to cognitive decline and is likely exacerbated by high levels of cytotoxic lipids that contribute to insulin resistance." (PMID 41294899, 2025). "Intensive glycemic control through lifestyle modifications, oral hypoglycemic agents, and/or insulin therapy can improve cognitive function and slow cognitive decline in diabetics." (PMID 39822993, 2025). "Elevated Aβ levels further impair insulin signaling, creating a vicious cycle that accelerates cognitive decline." (PMID 40008362, 2025). "In contrast, APOE ε4-negative participants experienced a significant cognitive decline while on insulin." (PMID 41146261, 2025). "In a study comparing the effects of Vildaglipti and Dapagliflozin, it was shown that single treatment of either drug resulted in improved brain mitochondrial function, insulin signaling, apoptosis and prevented cognitive decline." (PMID 39897964, 2024).
cognitive decline (continued). "Conclusion: “The results suggested that the restoration of insulin activity represents a promising therapeutic target for improve cognitive decline in AD”." (PMID 38425702, 2024). "We previously reported that milk‐derived YLG used to improve cognitive decline induced by HFD intake increased insulin sensitivity in the ITT." (PMID 38974115, 2024). "SGLT-2 inhibitors improve glycemic control, enhance insulin sensitivity, and reduce AGEs and oxidative stress, potentially mitigating cognitive decline." (PMID 39728750, 2024). "Furthermore, mitochondrial dysfunction in the brain (e.g., excess reactive oxygen species, mitochondrial depolarization, and swelling) is closely related to brain insulin resistance, and these pathological processes may contribute to cognitive decline and increase the risk of AD." (PMID 39634656, 2024). "Conversely, diets high in saturated fats and refined sugars can lead to dysbiosis, increased intestinal permeability, and systemic inflammation, contributing to insulin resistance and cognitive decline." (PMID 39659426, 2024). "Insulin treatment effectively mitigated LPS‐induced cognitive decline and safeguarded against neuronal degeneration." (PMID 39073013, 2024). "A balanced dietary approach utilizes multiple mechanisms to support the brain optimally to prevent and reverse cognitive decline by mechanisms such as increased energy, insulin sensitivity, reduced inflammation, improved vascular health, and detoxification." (PMID 36675177, 2023). "This approach utilizes multiple mechanisms to support the brain to prevent and reverse cognitive decline, such as increased energy (via ketosis), insulin sensitivity, reduced inflammation, improved vascular health, and detoxification." (PMID 36675177, 2023). "Mechanistically, reduced adipose expandability leads to hypertrophic adipocytes, triggering inflammation, insulin and leptin resistance, blood-brain barrier disruption, altered brain metabolism, neuronal inflammation, brain atrophy, and cognitive decline." (PMID 38026693, 2023). "An animal study of intranasally administered metformin for four weeks showed the mechanism behind its effect of ameliorating cognitive decline in the AD mice models through brain insulin signaling." (PMID 37511207, 2023). "Thiazolidinediones are another frequently prescribed insulin sensitizer that is now being studied for their impact on cognitive decline." (PMID 37511207, 2023). "We and others have shown that knockout of FABP4 leads to an alleviation of HFD-induced peripheral and central inflammation, insulin insensitivity, and cognitive decline." (PMID 36834799, 2023). "For example, cognitive decline was restored after vildagliptin administration in insulin-resistant obese subjects." (PMID 38082288, 2023). "This is important as IN insulin is being pursued in the clinic for the prevention of cognitive decline." (PMID 37076875, 2023). "A study in animals highlighted the superiority of intranasal insulin over parenteral insulin as a treatment for cognitive decline." (PMID 37511207, 2023). "Transgenic mice overexpressing the human APP gene display defects in peripheral insulin sensitivity before amyloid‐β accumulation in the brain and cognitive decline." (PMID 37095621, 2023). "There are also additional factors including mitochondrial dysfunction, insulin resistance, metabolic dysregulation and neuroinflammation that contribute to cognitive decline in AD10,27,28." (PMID 36396721, 2022). "The high content of unsaturated fatty acids in nuts can exert neuroprotective effect by influencing insulin sensitivity and reducing inflammation, which are involved in the development of cognitive decline." (PMID 35493926, 2022). "Regarding the relevance of the APP/PS1 transgenic mouse as an experimental AD model, a previous study showed that impaired glucose tolerance and reduced insulin sensitivity precede amyloid plaque deposition and cognitive decline in these mice." (PMID 35875664, 2022).
cognitive decline (continued). "Cognitive decline is associated with serine phosphorylation of IRS1 and co-localized with neurofibrillary tangles, decreasing insulin actions by changes in the PI3K signaling pathway." (PMID 36233271, 2022). "Intranasal insulin also slowed the development of cognitive decline in different disease models and improved learning and memory in wildtype mice." (PMID 34834319, 2021). "Additional enrichment analysis (FUMA) of the genes mapped from the SNPs in the fasting insulin rPRS showed enrichment with the accelerated cognitive decline GWAS." (PMID 34539334, 2021). "The decreased insulin signaling in the hippocampus resulted in cognitive decline accompanied with decreased mitochondrial oxidative phosphorylation complex proteins." (PMID 34108878, 2021). "Intranasal insulin administration has been proved to ameliorate cognitive decline in AD subjects and the effects are even better when insulin is administered in the early stages of the pathology (e.g., MCI)." (PMID 32733190, 2020). "Collectively, these observations suggest that insulin is a protective factor for brain function, and insulin signaling is an important pathway in the prevention of cognitive decline." (PMID 32083135, 2020). "Many studies have drawn a strong link between insulin resistance and cognitive decline, especially in the elderly." (PMID 31440156, 2019). "Regardless, in both cases, dysfunctional Tau protein and insulin signaling would aggravate each other and prompt or exacerbate cognitive decline in AD and other tauopathies." (PMID 30804755, 2019). "Although the influence of Tau pathology on insulin signaling is not completely understood, it is known that insulin resistance can induce Tau hyperphosphorylation and cognitive decline in human and in animal models." (PMID 30804755, 2019). "Impaired insulin (InsR) and insulin growth factor receptor (IGF-1R) signaling via pAkt/Akt has been linked to cognitive decline in normal aging, as well as AD." (PMID 30631278, 2018). "Information as it is, it would point out that, impairment in insulin signalling and glucose metabolism, in central as well as peripheral systems, would be one of the reasons for the cognitive decline." (PMID 29382127, 2018). "Epi's positive effect on insulin signaling in mammals possibly also plays a role in increasing cognitive ability or slowing down cognitive decline seen in aged individuals." (PMID 29497476, 2018). "Among these, four regions (the orbitofrontal gyrus, right middle cingulate gyrus, right hippocampus, and right precuneus) had significant interaction with insulin resistance, resulting in cognitive decline." (PMID 30400348, 2018). "In the full models controlled for many related confounding factors such as nutritional status, kidney function, inflammation, insulin resistance, and hemoglobin, this interrelationship between subjective cognitive decline and frailty remained unchanged." (PMID 30071051, 2018). "Brain mitochondria are also damaged as a result of an obese-insulin resistant condition with resulting cognitive decline." (PMID 30233495, 2018). "For example, intranasal insulin administration has been demonstrated to improve glucose uptake and age-related cognitive decline in older people and aged animals." (PMID 29238302, 2017). "Nevertheless it should be noted that insulin has been proposed to have a protective effect in the brain against cognitive decline, at least in older people." (PMID 27479051, 2016). "Increased Aβ production further disrupts insulin signaling to exacerbate the AD pathology and cognitive decline." (PMID 27936074, 2016). "Our work underscores the importance of connecting ApoE genotype and insulin sensitivity as an early marker for AD-related cognitive decline." (PMID 27189808, 2016). "Here, we investigated the association over time between changes in plasma levels of IGF-1 and insulin and the cognitive decline in HD patients." (PMID 27627435, 2016).
cognitive decline (continued). "In conclusion, adiponectin improves impaired insulin signaling and improves cognitive decline as a typical feature of vascular dementia." (PMID 24860814, 2014). "Cognitive decline was compared between patients with mild-to-moderate AD and DM treated with insulin (n = 55) and those on oral hypoglycaemic agents alone (n = 49)." (PMID 25385407, 2014). "Following this pathway, early treatment intranasal insulin has actually shown some promise in treating cognitive decline." (PMID 25179671, 2014). "It is becoming increasingly clear that the central roles in the process of synaptic dysfunction, neuronal death and cognitive decline are played by the brain's impaired glucose utilization, insulin resistance, lipid metabolism alterations, and energy homeostasis disruption." (PMID 41835065, 2026). "Recent research has provided substantial evidence linking insulin resistance to cognitive decline." (PMID 40076550, 2025). "The interplay between insulin resistance and neuroinflammation establishes a detrimental feedback loop, wherein each process exacerbates the other, accelerating neuronal dysfunction and cognitive decline in AD." (PMID 40724831, 2025). "However, a recent review suggests that over-nutrition leads to cognitive decline by affecting insulin resistance, gut-brain axis, and neuroinflammation." (PMID 39963661, 2025). "Intranasal insulin (INI) has emerged as a potential treatment for T2DM-related cognitive decline." (PMID 40392946, 2025). "Impaired insulin signalling may lead to neuroinflammation along with the cognitive decline, because insulin plays a imperative role in metabolism in brain and neuronal health." (PMID 40771585, 2025). "Furthermore, insulin resistance in neural cells disrupts normal insulin signaling, and impairs the suppression of β-amyloid production and tau protein hyperphosphorylation, promoting cognitive decline." (PMID 41234238, 2025). "In this sense, it has been reported that cognitive decline might be worsened in patients who only receive oral antidiabetic drugs when compared with those on combined therapy (oral antidiabetic + insulin)." (PMID 41146261, 2025). "Endothelial dysfunction and arterial stiffness diminish cerebral perfusion and impair neurovascular coupling, while glymphatic clearance of Aβ is reduced by insulin resistance and chronic low-grade inflammation, together accelerating proteinopathy and cognitive decline." (PMID 41155642, 2025). "Currently, a phase II/III clinical trial (SNIFF: Study of Nasal Insulin to Fight Forgetfulness) is underway in amnestic MCI and mild AD patients to find out the outcome of intranasal insulin on changes in CSF biomarkers, cognitive decline, and brain volume loss (NCT01767909)." (PMID 40546882, 2025). "Our findings suggest that the parameters related to glucose and insulin regulation could play an important role in neurodegeneration and cognitive decline." (PMID 40771353, 2025). "Nut products, rich in unsaturated fatty acids, may help prevent cognitive decline by modulating insulin sensitivity and reducing inflammation." (PMID 40944157, 2025). "By comparing models of impaired insulin production and systemic resistance, we identified how these distinct metabolic disruptions contribute to neuroinflammation, synaptic dysfunction, and cognitive decline." (PMID 40964391, 2025). "First, it suggests that parameters related to glucose and insulin regulation might play an important role in neurodegeneration and cognitive decline." (PMID 40771353, 2025). "Ultimately, restoring insulin sensitivity in the brain may not only delay cognitive decline but alter the natural history of neurodegenerative disease." (PMID 41294899, 2025). "AngII has been implicated in disruption of insulin signaling in the brain, indicating that RAS activation may also contribute to cognitive decline by altering insulin sensitivity." (PMID 41178713, 2025).